CD68 (CD68 molecule)
Diseases named in the same sentence as CD68 in open-access papers (continued):
Sharing a sentence is not in itself a finding about the gene and the disease.
tumor (continued). "Correspondingly, the immunosuppressive cytokine IL-10 showed a significant increase in expression through progression, and this correlated with greater numbers of putatively tumor-promoting neutrophils (elastase) and macrophages (CD68)." (PMID 35379804, 2022). "Here, we observed increased numbers of CD68+ macrophages in invasive tumours compared to high-grade IPN and BilIN." (PMID 36068277, 2022). "We evaluated tumor immune cell infiltration by monitoring changes in the expression of Cd8a, Cd68, and Nkp46, immune cell markers for cytotoxic T cells, macrophages, and natural killer cells, respectively." (PMID 36187936, 2022). "Immunostaining with more specific biomarkers (like CK for tumor cell or CD68 for macrophages) is a potential solution." (PMID 35844508, 2022). "These evidences manifested that CD68+CD163+M2-like macrophages in peripheral blood were different from the alternatively activated M2 macrophages in issue or tumor microenvironment." (PMID 35928634, 2022). "We also observed phenotype shifting of TAMs from immune-suppressive CD68+CD163+ TAM2 to pro-inflammatory/anti-tumor CD68+CD163-TAM1." (PMID 36686751, 2022). "We performed immunohistological staining for CD8-, CD4-, and CD68-positive tumor-infiltrating immune cells and measured relative levels of cytokines produced in Sftpc-WT and Sftpc-KO mice." (PMID 35326737, 2022). "Immune and stromal cell populations included 2 populations: Macrophages 1 (c1: C1qa, C1qb, C3aR1, Cd68, Csf1r, Tlr2, and Cd86) and 2 (c6 + c9: Ccr7, Csf2rb, Il1b, and Cd74) expanded in PNs as a percentage of total tumor cells." (PMID 36134665, 2022). "Next, we analyzed the correlation between CD68 levels and immune cell infiltration in the tumor microenvironment in 33 cancer types." (PMID 35550532, 2022). "We also validated that FCER1G and CD68 are both highly expressed in tumor tissue and correlated with each other." (PMID 35120484, 2022). "Two antibody panels using multiplexed immunofluorescence were designed for the simultaneous detection of CD8+ T-lymphocytes, CD68+ macrophages, Cytokeratin (CK) for tumor cells, PD-L1 immune checkpoint andKi67 as a proliferation marker." (PMID 35681797, 2022). "Nevertheless, IHC was performed in consecutive sections, and visual analysis suggested similar CD68 and CD163 expression profiles in the same tumor sample, although CD68 seemed to be expressed in a larger proportion of macrophages." (PMID 36230752, 2022). "Since elevated TAM (CD68+) infiltration in breast stroma has been negatively correlated with clinic-pathological features, such as tumor size, HR status, histologic grade, and age, it has been disclosed as a prognosis factor in breast cancer patients." (PMID 36551522, 2022). "With progressive expansion of the VS and thus increasing tumor volume, the expression of the macrophage markers CD68 (r = 0.28, p < 0.0001) and CD163 (r = 0.19, p = 0.02) increased weakly." (PMID 36139588, 2022). "Most current reports consider CD8+T cells, FOXP3+T cells, and CD68+ macrophages to be the primary innate immune response in the tumor microenvironment." (PMID 36011316, 2022). "As expected, the proportion of tumor area positive for CD68 was significantly higher in OGC-IC NST than in Ctl-IC NST (mean: 10.1% vs. 0.9%, p < 0.001), and in OGC-MC compared to Ctl-MC (mean: 13.1% vs. 1.7%, p = 0.032)." (PMID 35697931, 2022). "FACS analysis of Gpr35ΔMΦ tumours showed significantly less CD68+ cells compared with Gpr35fl/fl tumours." (PMID 33758004, 2022). "If including only DSS patients, predictions were still observed regarding CD3 TIL cells (p = 0.028), FoxP3 TIL cells (p = 0.017) and CD68 tumor cells (p = 0.005)." (PMID 36289746, 2022). "In the current study, we observed a correlation between EMR1-TC and CD68+/CD163+ TAMs; EMR1-TC was a high-risk factor for tumor recurrence, especially in patients with macrophage-rich CRC." (PMID 36551877, 2022).
tumor (continued). "In several independent studies amount of intratumoral CD68+ TAMs were indicative for reduced tumor growth and better prognosis." (PMID 36686729, 2022). "Staining of CD8+ T cells, conventional CD4+FOXP3- T cells (Tconv cells), CD4+FOXP3+ regulatory T cells (Treg cells), CD20+ B cells, and CD68+ macrophages was performed, and cell density was evaluated in both the tumor and its stroma." (PMID 36201479, 2022). "Nuclear immunostaining was observed in a few cases, while most cases showed cytoplasmic immunostaining, especially in CD68-positive tumor-infiltrating cells, suggestive for phagocytosis of dead hepatocytes." (PMID 35458213, 2022). "We found a significant reduction of CD68 expression inside the tumor after 10 days of TRAM-34 administration compared to vehicle-treated mice." (PMID 36589283, 2022). "We identify the existence of osteoclast-like giant cells (OGC) which have high expressions of CD68 and CD163, the biomarkers of tumor-associated macrophages (TAMs)." (PMID 36148946, 2022). "For markers expressed in immune cells such as PD-1, CD3, CD68 and PD-L1, the respective IC-scores were evaluated in tumor area (IC-tumor) and in stroma area (IC-stroma) of the tumor tissues." (PMID 35184226, 2022). "All four TAM markers were significantly and positively associated with higher TIL density (p < 0.001), higher PD-L1 expression in tumor (p < 0.001) and stromal cells (p < 0.001 for CD68, IRF8 and CD163; p = 0.002 for CD206)." (PMID 36230752, 2022). "Taken together, these data indicated that PLIN2+CD68+TAMs were involved in tumor immune escape, which promoted the poor prognosis of patients." (PMID 35372038, 2022). "To further elucidate which cell types that constitute the increased amount of leukocytes, we immunostained the tumor tissues for macrophages (CD68) and T cells (CD3)." (PMID 35018481, 2022). "Tumor-associated macrophages (TAM) are frequently polarized toward a M2 phenotype, which express CD68 and CD163." (PMID 35248056, 2022). "In the present study, we quantified the infiltration of invading tumor front and of inner tumor stroma by CD68 expressing macrophages." (PMID 35406573, 2022). "Nine tumour samples contained both a high CD68/PD-L1 double-positive cell count and a high CD8/PD-L1 double-positive cell count." (PMID 35606463, 2022). "Immunofluorescence analysis of six TNBC samples after NAC showed CD56-positive natural killer (NK) cells, CD8-positive T cells, CD68-positive/HLA-DR-positive macrophages (M1 macrophages), and PanCK-positive tumor cells." (PMID 35754838, 2022). "Macrophages (CD68+ cells) were present in significant numbers both among tumor cells and in the immune infiltrate." (PMID 34636027, 2022). "Although all ROC tumors expressed tumor-associated macrophage markers (e.g., CD68), only ROC1 and ROC3 tumors expressed more CD206, a marker of tumor-associated M2 macrophages." (PMID 35902768, 2022). "Increased levels of tumor associated M2 macrophages (M2 TAM) in the pre-operative biopsy tissues, such as CD68 or CD163 positive macrophages, have been associated with reduced responses to therapy and more frequent non-pCR results." (PMID 36428702, 2022). "In the tumor-immune microenvironment, the PD-L1 expression is particularly frequent in CD68+ macrophages in comparison to other immune cell types." (PMID 36387259, 2022). "Upregulated levels of CD68 were observed in various cancer types, which were observed in the TCGA database and our tumor tissue chips." (PMID 35550532, 2022). "For example, a high CD163+/CD68+ ratio in the infiltrative margin of the tumor suggests a poor prognosis for the colorectal cancer patients." (PMID 36195882, 2022). "Both tumoricidal M1 and tumor-promoting M2 macrophages express CD68, while M2 polarization can be identified by CD163, CD204 and CD206 biomarkers." (PMID 36686729, 2022).
tumor (continued). "Here, we found that the high expression of PD-L2 in the stroma significantly increased the number of tumor-related CD68+ macrophages and CD4+Foxp3+ Treg regulatory T lymphocytes." (PMID 36606190, 2022). "This study identified that expression of CD8, GZMB and CD68 within 25 μm of tumour cells at the tumour centre were strongly predictive of survival." (PMID 36114487, 2022). "Immunohistochemical analyses of tissues from a cohort of PDAC patients confirmed a high prevalence of MARCO-positive cells in the tumor stroma that also co-expressed the pan-macrophage marker CD68 in the majority of investigated specimens (n = 10)." (PMID 36310582, 2022). "In our clinical study enrolling 60 HNSCC patients, we showed a high infiltration of CD68+ cells mainly composed of CD163+ M2 macrophages (more than 60%) in tumor patients." (PMID 35742830, 2022). "In this study, combined scores of stromal CXCL8 and tumour‐infiltrating macrophages (CD68+ cells) or systemic neutrophil counts significantly stratified patient survival." (PMID 35879507, 2022). "Combined high expression of GZMB and CD68 within 25 μm to tumour cells is an independent prognostic factor in CRC and of superior prognostic value to the well-established CD8 in TNM stage II cancers." (PMID 36114487, 2022). "The top three tumor types with CD68 expression positively correlated with stromal score were BLCA, BRCA, and GBM (P < 0.001)." (PMID 35550532, 2022). "Infiltration of macrophages and CD8+ T cells in the tumor microenvironment (TME) were detected by immunohistochemistry with anti-CD68 and anti-CD8 antibodies, respectively." (PMID 36138417, 2022). "We identified CD8-positive T cells and CD68-positive macrophages infiltrating into the tumor tissue as significant favorable prognostic factors for ICI treatment." (PMID 36437290, 2022). "Pearson correlation analysis further showed that OPN was positively associated with M2 macrophage markers (CD163, VSIG4, MS4A4A, CX3CR1, and MRC1) and tumor-associated macrophage (TAM) markers (CCL2, CD68, and IL10)." (PMID 35669197, 2022). "Immunofluorescence staining revealed colocalization of PKM2 and PD-L1 in the tumor tissue with high glycolysis, along with accumulation of CD68+ macrophages." (PMID 34862460, 2022). "IHC staining for CD68 showed cytoplasmic staining, diffusely distributed in the tumor stromal cells, and was used to label TAMs." (PMID 36372883, 2022). "Based on the immunohistochemical analysis of samples from patients with ccRCC, we further validated that FCER1G and CD68 are both highly expressed in tumor tissue and correlate with each other." (PMID 35120484, 2022). "We then quantified the total volume density of BrdU + cells, and the volume densities of CK7 + /BrdU + and CD68 + /BrdU + cells in selected lungs from rats with orthotopic MLL-large tumors or from tumor-free controls." (PMID 35551231, 2022). "Even though the ratio of SIGLEC1 to CD68 expression (SIGLEC1/CD68) correlated with tumor grade, patients with high SIGLEC1/CD68 ratios had improved overall survival." (PMID 36266311, 2022). "These higher CD45+ immune infiltrates induced by the MuSyC-dose treatment led to an enhanced percentage of CD8+ T cells, CD4+ T cells, NK cells, and CD68+ MACs in the tumor compared to the other groups." (PMID 36059502, 2022). "The clinical prognosis and immune infiltration of high expression levels of CD68 differ across tumor types." (PMID 35550532, 2022). "Tumor cells continue proliferating together with the tumor-infiltrating lymphocytes and other immune cells, including CD68+ macrophages, and CD3+ T and CD20+ B lymphocytes." (PMID 36429133, 2022). "Correlation analysis of the markers COX2, VEGF, Ki-67, CD163, CD68, GM-CSF and M-CSF with age, tumor volume, and hearing class were performed using Spearman’s rank correlation coefficient." (PMID 36139588, 2022).
tumor (continued). "Compared with the Chemo group, the Io+Chemo group demonstrated a significantly higher M1 macrophage density (CD68+CD163- cell subset) ratio in the tumor to that in the stroma (P = 0.0446)." (PMID 36275670, 2022). "CD14+ cells from tumour tissue have higher expression of the macrophage markers CD68, CD206 and CD163 but only CD163 was increased in patient blood CD14+ cells." (PMID 34727230, 2022). "It is important to note that many CD4+, CD8+, and CD68+ cells were infiltrated into tumor tissues from humanized NDG mice." (PMID 35229723, 2022). "Tumor macrophages expressed higher levels of CD68 and PPARγ and lower levels of HLA-DR compared to components that resided in adjacent tissues." (PMID 35874784, 2022). "Some authors considered CD68 immunostaining as a useful routine tool in the prediction of the outcome of FL patients with a high tumor burden who receive chemotherapy." (PMID 35268349, 2022). "High amounts of CD68+ TAMs in tumor nest correlated with recurrence in 184 cutaneous melanoma patients from Finland." (PMID 36686729, 2022). "Other studies describe similar findings for macrophage markers, such as CD68, commonly expressed by tumor cells in histopathological sections." (PMID 36499015, 2022). "In order to quantify the percentage of macrophages infiltration in the tumor patients, ratios were calculated between the number of CD68+ cells and the total number of cells by field (0.1 mm2)." (PMID 35742830, 2022). "While the tumor-associated macrophage (TAM) markers, as well as CD68 and HLA-DRA as both M1/M2 and tumor-associated macrophage (TAM) markers were highly expressed in each macrophage subtype, indicating they were all TAMs." (PMID 35361264, 2022). "An interesting mechanism in PCa-macrophages crosstalk involved semaphorin 3A (SEMA3A) which is produced by cancer cells and recruit monocytes to the tumor site where acquire a pro-tumoral CD68+ M2-like phenotype." (PMID 36338516, 2022). "Apart from CD68, other immunological markers were rarely expressed, suggesting a low level of tumor-infiltrating lymphocytes in ASPS." (PMID 35628499, 2022). "The scores for each cell type in the tumor microenvironment showed the following ratios: CD3+:CD20+:CD138+:CD56+:CD68+:MPO = 0.44: 0.13: 0.09: 0.09: 0.22: 0.03." (PMID 34636027, 2022). "Staining for CD68 in the FFPE tumour tissue from our cohort found a trend for an increased percentage of CD68+ cells in tumours of BE-GICs relative to nBE-GIC tumours." (PMID 36412091, 2022). "We sought to compare the prognostic value of CD8 with downstream indicators of active immune cell function, specifically granzyme B (GZMB) and CD68 in the tumour microenvironment." (PMID 36114487, 2022). "We then investigated tumor infiltration of monocyte/macrophages using IHC staining for the monocyte/macrophage marker CD68 and found significantly reduced infiltration of CD68+ cells in Tlr2−/− tumors." (PMID 36351380, 2022). "The weak signal of IRDye700DX-PSMA detected in the PSMA(−) PC3-FLU tumour displayed a good colocalization with the CD68 macrophage marker." (PMID 36361667, 2022). "Specifically, we analyzed CD4+/Foxp3+ T regulatory cells (T-regs), CD4+/Foxp3− helper T cells (Th-cells), CD8+ cytotoxic T cells (Tc-cells), CD20+ B-cells, CD68+ macrophages, and CK+ tumor cells." (PMID 35565427, 2022). "The top three tumor types with CD68 expression positively correlated with immune score were ACC, BLCA, and BRCA (p < 0.001)." (PMID 35550532, 2022). "Particularly, the M2 phenotype (CD163) with anti-inflammatory activity contributes to a favorable microenvironment for tumor development while the M1 (CD68) proinflammatory phenotype contributes to a restrictive one." (PMID 36451810, 2022).
tumor (continued). "A lower degree of infiltration of PD-L1+CD68+ cells was seen in both tumor and stroma in the Io+Chemo over in the Chemo (density: tumor, P = 0.0462, stroma, P = 0.0147, total, P = 0.0248; percentage: tumor, P = 0.0537, stroma, P =0.0171, total, P = 0.0156)." (PMID 36275670, 2022). "Intra-, and peritumoural CD8-positive, PD-L1 and CD68-positive cell counts are signs of tumour inflammation and are potential biomarkers for immune-modulating agents." (PMID 35606463, 2022). "In the specimens, a higher number of tumor‐infiltrating CD68+ macrophages was observed in the RFA group compared with that of the non‐RFA group, and the macrophages demonstrated increased infiltration around the ablated zone." (PMID 35037422, 2022). "Immunohistochemistry and flow cytometry were employed to detect the expression of PD-1, Treg cells, CD8, and CD68 in tumor tissues, and the contents of PD-1+ CD8+ T cells, PD-1+ CD4+ T cells, and PD-1+ Treg cells in the peripheral blood." (PMID 35619918, 2022). "In this research, the expression levels of tumor-associated macrophages (TAMs)-related markers (CCL2, CD68 and IL10) were a positive correlated PKIA expression, indicating an ontogenetic role of PKIA in HCC." (PMID 36204642, 2022). "Upregulated CD68 levels were observed in various cancer types, which were verified through tumor tissue chips using immunohistochemistry." (PMID 35550532, 2022). "The peri-tumor lesions stained positively for CD68, whereas the majority of tumor cells and hepatic cells stained negatively." (PMID 36142683, 2022). "Combination or AXL-CAR T treatment induced downregulation of CD206+ expression from CD68+ macrophages in tumours, which is consistent with decreased M2 polarization." (PMID 36261437, 2022). "CD68- and CD163-labeled tumor-associated macrophages (TAMs) have both tumor-promoting and antitumor effects on tumors, and they both have significant correlation with prognosis." (PMID 36195882, 2022). "Conversely, a significant increase in CD68+ macrophages was observed in invasive tumours compared to BilIN (P = 0.007)." (PMID 36068277, 2022). "Next, we explored the relationship between CD68 expression and immune infiltrates in the tumor microenvironment in 33 tumor types based on the TIMER2.0 database." (PMID 35550532, 2022). "This demonstrated higher CD68 in the stroma of TNBC PDLIM2-positive tumours than in PDLIM2-negative tumours." (PMID 36531051, 2022). "We analyzed CD68 expression among 33 tumor and normal tissues from The Cancer Genome Atlas and Genotype-Tissue Expression datasets." (PMID 35550532, 2022). "It was demonstrated that PFKFB3 is predominantly expressed on CD14+CD68+ monocyte-derived macrophages that massively infiltrate tumor tissue." (PMID 36733385, 2022). "Multiplex immunofluorescence (IF) for PD-L1 and CD68 in DDIR-positive tumours confirmed that the majority of the PD-L1 expression co-localised with macrophages." (PMID 34728791, 2022). "The top three tumor types with CD68 expression positively correlated with the estimate score were BLCA, BRCA, and CESC (P < 0.001)." (PMID 35550532, 2022). "We found that EMR1-TC was more correlated with CD68+/CD163+ TAMs than with CD3+/CD8+ tumor-infiltrating lymphocytes, and this relationship was more significant in the tumor center than in the tumor-invasive area (data not shown)." (PMID 36551877, 2022). "Our results confirmed the previous findings that the expression of CD68 in tumor tissue was significantly higher than that in healthy adjacent tissue (ANOVA, p < 0.05)." (PMID 36230558, 2022). "First, to fully clarify the expression of CD68 in pan-cancer, we matched the GTEx normal samples with TCGA tumor samples." (PMID 35550532, 2022). "Compared with the vehicle, the expression of CD68 and F4/80 was significantly reduced in anti‐Chi3L1 antibody‐treated tumor tissues." (PMID 34861103, 2022).